MAPK1IP1L (mitogen-activated protein kinase 1 interacting protein 1 like)
Synonyms: C14orf32; MISS; c14_5346
Tractability: PROTAC: its protein half-life has been measured.
Gene: Protein-coding gene on chromosome 14 (55,051,647 to 55,070,194, forward strand). Ensembl gene ENSG00000168175.
Subcellular location (Human Protein Atlas): Cytosol; Nucleoplasm
Gene Ontology:
Molecular function: protein binding
Genetic constraint (gnomAD): Loss-of-function variants: 6 observed, 15.75 expected, observed/expected ratio (o/e) 0.38, 90% interval 0.21 to 0.75. The upper end of that interval is the gene's LOEUF score, 0.75, which puts it in group 3 of 6, group 1 being the genes least tolerant of losing a copy. Missense variants: 256 observed, 324.58 expected, observed/expected ratio (o/e) 0.79, 90% interval 0.71 to 0.88. Synonymous variants: 115 observed, 119.06 expected, observed/expected ratio (o/e) 0.97, 90% interval 0.83 to 1.13.
Homologues: Orthologues: chimpanzee MAPK1IP1L (100% identical), dog MAPK1IP1L (98% identical), macaque MAPK1IP1L (98% identical), pig MAPK1IP1L (95% identical), rabbit MAPK1IP1L (95% identical), guinea pig MAPK1IP1L (84% identical), mouse Mapk1ip1l (80% identical), rat Mapk1ip1 (47% identical), mouse Mapk1ip1 (44% identical).
Diseases named in the same sentence as MAPK1IP1L in open-access papers:
MAPK1IP1L is named in the same sentence as 4 diseases in open-access papers, as found by Europe PMC text mining. Sharing a sentence is not in itself a finding about the gene and the disease. The quoted sentences say what the papers report.
lung carcinoma (4 papers, 2021 to 2025). "A study of five urinary biomarkers, including MAPK1IP1L, may serve as a basis for the adjunctive diagnosis of lung cancer." (PMID 41262242, 2025). "Urine proteome profiling showed that high proportions of MAPK1IP1L could distinguish lung cancer patients from control and other cancers." (PMID 38584220, 2024). "Zhang’s group selected a panel of five urinary molecules (ferritin light chain, mitogen-Activated Protein Kinase 1 Interacting Protein 1-Like, fibrinogen Beta Chain, two Member RAS Oncogene Family, RAB33B and RAB15) as a predictive model to differentiate lung cancer from healthy lung tissue." (PMID 33923502, 2021).
MAPK1IP1L also shares sentences with these, for which no sentence is quoted: breast carcinoma (1 paper); cancer (1); tumour (1).